CNTRL (centriolin)
Description:
Involved in cell cycle progression and cytokinesis. During the late steps of cytokinesis, anchors exocyst and SNARE complexes at the midbody, thereby allowing secretory vesicle-mediated abscission.
Synonyms: Cep110; CEP1; FAN; bA165P4.1
Tractability: Antibody: its Gene Ontology location is reachable by antibodies, with high confidence. PROTAC: ubiquitination databases record sites on it; its protein half-life has been measured.
Gene: Protein-coding gene on chromosome 9 (121,074,660 to 121,177,729, forward strand). Ensembl gene ENSG00000119397.
Subcellular location: Cytoplasm, cytoskeleton, microtubule organizing center, centrosome; Midbody, Midbody ring
Subcellular location (Human Protein Atlas): Basal body; Centrosome; Flagellar centriole; Centriolar satellite; Cytosol; Golgi apparatus; Plasma membrane
Pathways (Reactome):
Cell Cycle: AURKA Activation by TPX2; Loss of Nlp from mitotic centrosomes; Loss of proteins required for interphase microtubule organization from the centrosome; Recruitment of NuMA to mitotic centrosomes; Recruitment of mitotic centrosome proteins and complexes; Regulation of PLK1 Activity at G2/M Transition
Disease: Signaling by FGFR1 in disease; Signaling by cytosolic FGFR1 fusion mutants
Organelle biogenesis and maintenance: Anchoring of the basal body to the plasma membrane
Gene Ontology:
Molecular function: protein binding
Cellular component: centriolar subdistal appendage; centrosome; membrane; cytosol; microtubule organizing center; cytoplasm; Flemming body; meiotic spindle; meiotic spindle pole; microtubule cytoskeleton; mitotic spindle pole; perinuclear region of cytoplasm
Genetic constraint (gnomAD): Loss-of-function variants: 186 observed, 252.98 expected, observed/expected ratio (o/e) 0.74, 90% interval 0.65 to 0.83. The upper end of that interval is the gene's LOEUF score, 0.83, which puts it in group 3 of 6, group 1 being the genes least tolerant of losing a copy. Missense variants: 2,124 observed, 2,359.1 expected, observed/expected ratio (o/e) 0.9, 90% interval 0.87 to 0.93. Synonymous variants: 779 observed, 838.32 expected, observed/expected ratio (o/e) 0.93, 90% interval 0.88 to 0.99.
Homologues: Orthologues: chimpanzee CNTRL (99% identical), macaque CNTRL (97% identical), guinea pig CNTRL (85% identical), dog CNTRL (85% identical), mouse Cntrl (81% identical), rat Cntrl (80% identical), tropical clawed frog cntrl (55% identical), zebrafish cntrl (18% identical).
Diseases named in the same sentence as CNTRL in open-access papers:
CNTRL is named in the same sentence as 11 diseases in open-access papers, as found by Europe PMC text mining. Sharing a sentence is not in itself a finding about the gene and the disease. The quoted sentences say what the papers report.
myeloproliferative disorder (2 papers, 2018 to 2023). A clonal hematopoietic stem cell disorder, characterized by proliferation in the bone marrow of one or more of the myeloid (i.e., granulocytic, erythroid, megakaryocytic, and mast cell) lineages. "A translocation between chromosomes 8 and 9 disrupts Centriolin function and is associated with stem cell myeloproliferative disorder (MPD)." (PMID 30687396, 2018).
breast carcinoma (1 paper, 2021). "Breast cancer patients with higher expression level of TTC34, CNTRL, TMEM151B, hsa-miR-5691, and hsa-miR-92a-1-5p showed the higher OS." (PMID 34055638, 2021). "The results suggested that metastasis associated RNAs, including AHRR, TTC34, CNTRL, ANKRD52, BCAR1, TMEM151B, PANX2, hsa-miR-105-5p, hsa-miR-4435, hsa-miR-5691, hsa-miR-92a-1-5p, and LINC01742 could serve as the prognostic biomarkers of breast cancer patients." (PMID 34055638, 2021).
chronic kidney disease (1 paper, 2023). Impairment of the renal function secondary to chronic kidney damage persisting for three or more months. "The other interesting alternatively spliced genes were engaged in chemical carcinogenesis (ARAF), chronic kidney disease (NEK8) and kidney development (CNTRL, TET2, NLE1)." (PMID 38074096, 2023).
chronic myeloid leukemia (1 paper, 2024). "For example, ZMYM2::FGFR1 most commonly presents as a T-lymphoblastic leukemia/lymphoma, BCR::FGFR1 and TPR::FGFR1 present histologically similar to chronic myeloid leukemia (CML), and CEP43::FGFR1 and CNTRL::FGFR1 show features similar to chronic myelomonocytic leukemia (CMML)." (PMID 38611061, 2024).
glioblastoma (1 paper, 2022). The most malignant astrocytic tumor (WHO grade IV). "For the remaining seven DEPCGs (ZWILCH, RPGR, ZNF460, ZNF528, QTRT2, C5orf15 and CNTRL), no previous functional associations were found with glioblastoma progression, despite a number of them being associated with other cancer types." (PMID 36497269, 2022).
CNTRL also shares sentences with these, for which no sentence is quoted: tumor (4 papers); cancer (2); chronic myelomonocytic leukemia (1); depression (1); infection (1); lymphoma (1).